NLRP3 (NLR family pyrin domain containing 3)
Diseases named in the same sentence as NLRP3 in open-access papers (continued):
Sharing a sentence is not in itself a finding about the gene and the disease.
tumor (continued). "Molecular docking and co-immunoprecipitation validated the interaction between TMEM71 and NLRP3, while multiplex immunofluorescence showed co-localization of these proteins in tumor cells." (PMID 39951856, 2025). "GMDP signals through NOD2 on myeloid cells to release IL-1b and NLRP3 to induce cytotoxic granzyme B+CD8+ T cells in the tumor and enhances the efficacy of anti–CTLA-4, anti–PD-1, and anti–PD-L1 in different mouse tumor models." (PMID 39895632, 2025). "Elevated expression of NLRP3 correlates with enhanced tumor growth, lymph node metastasis, and IL-1β expression; conversely, NLRP3 knockdown impairs proliferation, invasion, and metastatic capacity both in vitro and in vivo." (PMID 41560727, 2025). "In both genotypes (WT and KO) and treatment groups (Veh and Bc), CD163+ Toe-Macs were detected within tumor regions expressing high levels of NLRP3, IL-1β, TGF-β1, CCL2, IL-6, and PD-L1." (PMID 40794443, 2025). "Translationally, human and murine evidence suggests that Pg burden correlates with worse OS/RFS and that Pg-driven tumor promotion depends on hematopoietic NLRP3 signaling." (PMID 41440353, 2025). "The secretion of IL-18 by NLRP3 in Kupffer cells plays a key role in promoting NK cell maturation and enhancing their tumor-killing activity." (PMID 40141358, 2025). "Future studies should examine how tRNA modifications influence NLRP3 inflammasome activation by performing RNA sequencing in tumor tissues with varying levels of NLRP3 expression." (PMID 40718836, 2025). "Given the involvement of the NLRP3 inflammasome in numerous inflammatory and tumor conditions, the development of molecules capable of modulating its activity has become a central goal of pharmacological research." (PMID 41560727, 2025). "NLRP3 activity is central to this relationship in multiple tumour types, due to its role in coupling inflammasome activation to EMT via IL-1β–dependent signalling that engages NF-κB, TGF-β/Smad, and Wnt/β-catenin pathways." (PMID 41148809, 2025). "Here, IVM, which acts as a positive allosteric modulator of P2X4R, is a U.S. Food and Drug Administration (FDA)-approved antiparasitic drug that enhances NLRP3 inflammasome signaling, while MnO2 alleviates tumor hypoxia to preserve eATP levels." (PMID 41209313, 2025). "On the other hand, the NLRP3 inflammasome acts as a molecular sensor, triggering pyroptosis, which can both promote and hinder cancer progression depending on the tumor microenvironment." (PMID 41465546, 2025). "Given ATP’s role as a ubiquitous energy source, it is challenging to selectively modulate eATP levels to sustain P2X7R/NLRP3 signaling and enhance chemotherapy-induced immunogenicity in the tumor microenvironment (TME)." (PMID 41209313, 2025). "NLRP3 activation in GBM induces granulocyte-dependent tumor immunosuppression and antagonizes the therapeutic efficacy of STING activation." (PMID 40377974, 2025). "For instance, a pan-cancer study demonstrated that NLRP3 expression varies across tumor types, with its activity either elevated or suppressed depending on the cancer type." (PMID 40141358, 2025). "Mechanistic studies confirmed that suramin suppresses NLRP3 expression, thereby inhibiting tumor progression." (PMID 40718836, 2025). "This aligns with evidence on NLRP3 inflammasome activation in tumor progression via IL-1β and IL-18 maturation." (PMID 41373809, 2025). "NLRP3 inflammasome activation is well known to play a dual role in cancer immunity, promoting both inflammatory anti-tumor responses and, in some cases, tumor progression depending on the microenvironment." (PMID 41280918, 2025). "Aberrant expression and mutations of PANoptosis-related genes (PRGs), such as NLRP3, caspase-8, and TNFAIP3, have been identified across various cancers, with many PRGs acting as tumor risk factors." (PMID 39966334, 2025).
tumor (continued). "Taken together, these findings emphasize the central role of NLRP3 in driving both intrinsic tumor properties and extrinsic inflammatory cues in OSCC, offering a strong rationale for targeting this inflammasome in future therapeutic strategies." (PMID 41560727, 2025). "Recent evidence has increasingly implicated the NLRP3 inflammasome in the pathogenesis of OSCC, highlighting its dual role in promoting both chronic inflammation and tumor progression." (PMID 41560727, 2025). "For example, the ZDHHC1 gene suppresses tumor growth by inducing ERS-pyroptosis, while ginsenosides and flavonoids inhibit pyroptosis in diabetes-associated tumors by modulating the ERS-TXNIP/NLRP3 axis." (PMID 41407677, 2025). "NLRP3 inflammasome is a key regulator of inflammation in this cancer for enhance tumor cell growth, survival, migration, and invasion by regulating autophagy, mitochondrial metabolism, EMT, angiogenesis, immune evasion, and metastasis." (PMID 41560727, 2025). "Knockdown of NIMA-related kinase 7 (NEK7) activates the NLRP3/caspase-1/GSDMD axis to inhibit tumor progression." (PMID 40806716, 2025). "As a specific NLRP3 inhibitor, Dapansutrile effectively suppresses the inflammasome pathway via oral administration, thereby remodeling the tumor microenvironment (TME)." (PMID 41415576, 2025). "In particular, the activation of NLRP3 in dendritic cells (DCs) showed an anti-tumor activity via IL-1β/Th1/IFNγ." (PMID 39857785, 2025). "In the GSE53819 dataset, 26 NRGs were identified, correlated with NLRP3 expression, and downregulated in tumor tissues." (PMID 39951856, 2025). "In EG7-OVA tumor-bearing mice, CpG/ZANPs exhibited remarkable tumor suppression through concurrent NLRP3 inflammasome activation and cGAS-STING-dependent type I interferon (IFN) production, effectively overcoming conventional alum’s Th1 response limitations." (PMID 40422849, 2025). "In terms of patterns among inflammasome components, NLRP3 predominantly exhibits pro-tumor effects across multiple cancers, whereas AIM2 largely shows anti-tumor activity." (PMID 41291696, 2025). "Autophagy activation at MAMs can remove damaged mitochondria, preventing NLRP3 inflammasome activation and influencing tumor progression." (PMID 40671967, 2025). "This suggests that NLRP3 activation and subsequent IL-1 signaling during AC are crucial for the expansion and suppressor function of MDSCs, as previously shown for tumor-induced MDSCs." (PMID 40530419, 2025). "NLRP3 inhibition is another therapy with potential combined anti‐tumour and cardioprotective properties." (PMID 40069106, 2025). "This context-dependent functional divergence highlights the importance of considering the specific characteristics of the TME when evaluating the role of NLRP3 across different tumor types." (PMID 40718836, 2025). "NLRP3 has emerged as a critical factor influencing tumor progression, functioning through both pro- and anti-tumorigenic pathways." (PMID 40155968, 2025). "For instance, in macrophages and endothelial cells, curcumin inhibits NLRP3 activation and reduces pro-inflammatory cytokine secretion, thereby attenuating chronic inflammation in the tumor microenvironment." (PMID 40806716, 2025). "The promotion of tumor cell mutagenesis and acceleration of tumor growth are facilitated by the inflammatory response, whereas the NLRP3 inflammasome regulates immune factors during pyroptosis to sustain homeostasis." (PMID 40698137, 2025). "IL-1β is central to inflammasome activation and tumor-promoting inflammation via NLRP3 and NF-κB signaling." (PMID 41401147, 2025). "For example, miR‐223 is a well‐documented miRNA that suppresses NLRP3 expression, thereby reducing the activation of the inflammasome and the consequent release of IL‐1β in tumor‐infiltrating macrophages and myeloid‐derived suppressor cells." (PMID 40671967, 2025).
tumor (continued). "Since the alteration of Ca2+ levels can also induce NLRP3 activation, it is likely that the whole complex can participate to resistance to chemotherapy (tumor progression) via the activation of the inflammasome." (PMID 39857785, 2025). "In conclusion, the NLRP3 inflammasome plays a pivotal role in the development and progression of urogenital system tumors, with its regulatory mechanisms involving tumor cell proliferation, apoptosis, immune evasion, and inflammatory signaling." (PMID 40718836, 2025). "2GBI treatment alone promoted anti-tumor immunity and inhibited tumor growth via NLRP3-dependent manner." (PMID 40185713, 2025). "NLRP3 inflammasome signaling plays an important role in tumor progression and the response of the tumor to chemotherapy treatment." (PMID 40104043, 2025). "In comparison to their chitosan-treated WT counterparts, Nlrp3-/- mice exhibit notably larger tumor volumes and tumor weights, thereby underscoring the pivotal role of NLRP3 in mediating the antitumor effect of chitosan." (PMID 40860135, 2025). "Immunofluorescence staining indicated that expression levels of C-Caspase-1, N-GSDMD, and NLRP3 were significantly elevated in tumor tissues treated with THZO NWs, with even greater enhancement in the THZO + US group." (PMID 41402300, 2025). "As discussed in Section 2 and Section 3, receptors such as TLR2, TLR4, TLR7, TLR9 and NLRP3 generally promote tumor progression and immune suppression." (PMID 41157253, 2025). "In summary, during efferocytosis, downstream effects of NLRP3/Caspase‐1/IL‐1β signaling axis in macrophages promote tumor growth in vivo." (PMID 39748782, 2025). "This chronic inflammation, characterized by persistent activation of NF-κB and NLRP3 inflammasome pathways, fosters a tumor-promoting microenvironment." (PMID 41487586, 2025). "In fact, AIM2, NLRP3 and RIG-1 were overexpressed in EBV-associated NPC and were interestingly reported to possess anti-tumour effects in EBV-associated NPC via IL-1β release." (PMID 41440367, 2025). "Persistent pyroptosis leads to sustained activation of NLRP3 inflammasomes, driving IL-1β overproduction, angiogenesis, and stromal remodeling, thereby creating an ecological niche for tumor metastasis." (PMID 41267084, 2025). "NETs are thought to induce the NLRP3 signalling pathway and the metastatic process by downregulating the expression of a specific tumour-suppressing long-coding RNA, MIR503HG." (PMID 41148809, 2025). "Conversely, NLRP3 activation exhibits anti-tumor effects in CRC liver metastasis via promoting NK cells, which underscores the unique characteristics of malignancies." (PMID 41291696, 2025). "With the in-depth research on TRP channels, the role of their downstream NLRP3 inflammasome and related pathways in tumor cell proliferation and metastasis has become relatively clear." (PMID 40718836, 2025). "Activation of NLRP3 can enhance immune responses by recruiting immune cells to the tumor, but chronic activation leads to sustained inflammation, promoting tumor growth, invasion, and metastasis." (PMID 41465546, 2025). "In CRC, A. muciniphila suppresses tumor growth by inducing the activation of the TLR2/NF-κB/NLRP3 pathway and promoting the accumulation of M1 macrophages." (PMID 39966840, 2025). "Concurrently, the inhibition of the NLRP3 inflammasome mitigates IL—1β—driven immunosuppression within the tumor microenvironment, while PD—1 blockade further promotes CD8+ T—cell infiltration by surmounting T—cell checkpoint inhibition." (PMID 40877572, 2025). "Here we show that a small molecule compound directly targeting NLRP3 can induce inflammasome activation and anti-tumor immunity." (PMID 40185713, 2025). "In a pan‐cancer analysis, 15 out of 24 cancers exhibited significantly different expression of NLRP3‐inflammasome‐related genes between normal and tumor samples." (PMID 40135589, 2025).
tumor (continued). "To demonstrate that the abnormally high expression of NLRP3 in tumor cells is a significant factor leading to tumor growth, we conducted subcutaneous tumor formation experiments in mice." (PMID 39744485, 2025). "For example, prostate cancer studies show significantly higher NLRP3 expression related with tumor cells proliferation and invasion." (PMID 41560727, 2025). "Our findings unequivocally demonstrate that chitosan exerts a significant inhibitory effect on tumor growth in wild-type (WT) mice; however, this antitumor activity is conspicuously diminished in Nlrp3-/- mice." (PMID 40860135, 2025). "Functional studies demonstrate that genetic silencing or pharmacological inhibition of NLRP3 enhances apoptosis and reduces tumor burden." (PMID 41560727, 2025). "Epigenetic downregulation of NLRP3/GSDMD by histone deacetylase 2 (HDAC2) can reduce anti-tumor therapeutic efficacy." (PMID 41291696, 2025). "Recent investigations have revealed a dual role of NLRP3 in cancer, acting variably as a tumor promoter or suppressor depending on cellular context and tumor type." (PMID 41560727, 2025). "An analysis of NLRP3 was reported across 24 cancers, 15 of which showed significantly different expression of NLRP3 inflammasome‐related genes between normal and tumor samples." (PMID 40671401, 2025). "Research indicates that ATP released by tumor cells treated with chemotherapy drugs activates NLRP3 inflammasomes and the IL‐1β receptor." (PMID 40671967, 2025). "Their findings highlighted that NLRP3 expression and activation were higher in cancerous tissues from 5-FU-treated patients, whose prognosis was poor according to the tumor stage and differentiation." (PMID 39857785, 2025). "NLRP3 plays a dual role in cancer, contributing to tumor-promoting inflammation and immune evasion while influencing immune surveillance." (PMID 40155968, 2025). "In this study, the positive correlation between ALKBH7 and NLRP3 suggests a link between mitochondrial stress and inflammation, contributing to immune suppression in the tumor microenvironment." (PMID 41373809, 2025). "For instance, KRAS mutations upregulate PD-L1 expression, aiding immune escape, and activate inflammasomes like NLRP3, which further promote a pro-tumor inflammatory milieu." (PMID 40538856, 2025). "For instance, the activation of the NLRP3 inflammasome after anthracycline treatment resulted in anti-tumor activity, whereas the administration of paclitaxel, 5-FU, or gemcitabine had opposite effects." (PMID 39857785, 2025). "This notion has been supported by some recently developed anti‐tumour therapies, particularly those that target the NLRP3 inflammasome, such as NLRP3 and IL‐1 inhibitors, which have also been shown to protect the cardiovascular system." (PMID 40069106, 2025). "We used Oncomine to analyze its differential expression between tumor samples and corresponding healthy controls to investigate the role of NLRP3 in CRC pathogenesis." (PMID 39744485, 2025). "The pro-tumorigenic role of NLRP5 in HCC contrasts sharply with NLRP3, which is generally considered tumor-suppressive through its inflammasome-activating properties." (PMID 41050084, 2025). "The parallel increase in α7nAChR and NLRP3 levels suggests that inflammation fosters a tumorigenic microenvironment in GI cancers, with these receptors potentially contributing to tumor migration and proliferation." (PMID 41003004, 2025). "Some microRNAs can affect the activation of pyroptosis by regulating the expression of pyroptosis-related proteins, thereby inhibiting tumor growth and metastasis, such as NLRP3 inflammasomes and GSDMD." (PMID 39834603, 2025). "Chronic inflammation is a well-established driver of colorectal tumorigenesis, and NLRP3-mediated inflammation contributes to this process by modulating the crosstalk between tumor cells and the immune milieu." (PMID 40869140, 2025).
tumor (continued). "TMEM71, identified in the GSE64634 and GSE102349 datasets, was downregulated in tumor tissues and positively correlated with NLRP3 expression." (PMID 39951856, 2025). "Collectively, these results suggest that Nlrp3 influences Th17 cell function in cancer and reduces tumor growth in an inflammasome-independent manner." (PMID 40195474, 2025). "Then, we further investigated the effects of melatonin and the NLRP3 pathway on tumor angiogenesis and lymphangiogenesis." (PMID 39230586, 2024). "In the context of immunotherapy, the tumor-intrinsic NLRP3-heatshock protein 70 (HSP70) toll-like receptor 4 (TLR4) axis has been associated with disease hyper-progression and survival in patients undergoing anti-PD-1 immunotherapy." (PMID 39769450, 2024). "The NLRP3 inflammasome has been extensively studied for its role in regulating tumors and shaping the tumor microenvironment." (PMID 39456655, 2024). "Higher levels of HIF-1α expression are associated with the NLRP3 inflammasome, EMT/metastasis, and Warburg effect in tumor cells." (PMID 38904007, 2024). "The same study also examined the role of the aryl hydrocarbon receptor (AHR) which has been detailed to be a potential tumour suppressor and NLRP3 regulator." (PMID 39516433, 2024). "In their experimental data, dietary cholesterol significantly increased the inflammatory response and tumor burden by stimulating the activation of NLRP3 inflammasomes in macrophages, thereby promoting oxidative azomethanes (AOM)-induced CRC." (PMID 38182564, 2024). "The mRNA and protein levels of NLRP3 pathway in the tumor tissues of each group were evaluated using RT-PCR and western blotting, respectively." (PMID 39230586, 2024). "We further used IHC to detect proliferation and EMT markers in tumor tissues and found that the expression of NLRP3 in OSCC exhibited a strong protective effect against OSCC development." (PMID 38697992, 2024). "In conclusion, the findings of this study suggest that the tumour inflammatory environment induced by hypoxia promotes IL37 expression via NLRP3 inflammasome activation, and IL37 release through NLRP3/GSDMD." (PMID 39500733, 2024). "ATP, via the P2X7R, activates the NLRP3 inflammasome, attracts immune cells, and primes the adaptive immune system, affecting DCs to support an anti-tumor response and inhibit tumor growth." (PMID 39456655, 2024). "These comorbidities combined with the overactivity of NLRP3 inflammasome attenuate the auxiliary anti-tumor effect of colchicine in patients with IMIDs." (PMID 38649928, 2024). "It was found that high NLRP3 level are correlated with tumor staging, distant metastasis, and vascular invasion of malignant tumors." (PMID 38182564, 2024). "Among them, the NLRP3 inflammasome has been widely reported in studies of tumor and neurological diseases." (PMID 38561456, 2024). "In this study, we evaluated the effects of NLRP3 inflammasome modulation on the anti-tumor activity of PTX in TNBC context, highlighting the interconnection between inflammatory mechanisms and tumor progression." (PMID 39433537, 2024). "Even more should be said, in view of this, about HSPs, specifically HSP70, that are also involved as an effector of NLRP3‐related pathways of inflammation as well as autoimmune pathways promoting tumor progression." (PMID 38775220, 2024). "It is worth noting that the research on NLR family including NLRP3 inflammasome in tumor targeted therapy has made significant progress." (PMID 39882240, 2024). "CXCL10 expression and its pathway components, NLRP3, NF-κB, and IL-1β, were markedly suppressed in tumor tissues from the calycosin-treated mice." (PMID 38461458, 2024). "Sophisticated tracking of infiltrating versus peripheral macrophages and CTLs is feasible in this model, allows intervention on a molecular level (such as NLRP3 activation), and establishes T cell motility as a readout parameter of tumor biology studies." (PMID 39796680, 2024).